FBP1 (fructose-bisphosphatase 1)
Diseases named in the same sentence as FBP1 in open-access papers (continued):
Sharing a sentence is not in itself a finding about the gene and the disease.
tumor (continued). "The data showed that the expression of only four out of 38 genes (HK3, FBP1, PKLR, GCK) was significantly affected by tumor purity (p < 0.01) but none of them was significantly differentially expressed between Gly and Non-Gly subtypes." (PMID 30873387, 2019). "This would explain our finding that the Ki-67 labeling index is related to FBP1 expression only in clear cell RCC, but not in other tumor subtypes." (PMID 19087307, 2008). "Besides, BGS also revealed that FBP1 promoter was heavily methylated in HepG2, Huh7, BEL-7402 cells and 8T tumor tissue, and no methylation was dedtected in 8N adjacent non-tumor tissue." (PMID 22039417, 2011).
cancer (99 papers, 2008 to 2025). A tumor composed of atypical neoplastic, often pleomorphic cells that invade other tissues. "Hypermethylation of the FBP1 promoter region is the primary cause behind FBP1 deletion in many cancers." (PMID 40100307, 2025). "The current understanding of the roles of FBP1 in the maintenance of the cancer stem cell phenotype and the associated regulatory mechanisms is lacking." (PMID 38349431, 2024). "Increased expression of ALDOA and decreased expression of FBP1 are associated with the progression of various forms of cancer in humans." (PMID 35404841, 2022). "Downregulation of FBP1 expression causes an increase in glycolysis and the number of cancer stem cells (CSCs)." (PMID 34363022, 2021). "Previous studies have shown that hypermethylation of the FBP1 promoter region is the main cause of loss of FBP1 in various cancers." (PMID 34363022, 2021). "As the gluconeogenesis by FBP1 is highly endergonic, the metabolic advantage by loss of FBP1 in cancer cells is quite clear." (PMID 32927665, 2020). "FBP1 was significantly associated with overall survival outcomes in 10 cancers while PPP2R2C and PPP2R2B in 8 cancers." (PMID 32807122, 2020). "Previous studies have found that FBP1 abnormal expression or loss of function is observed in various malignant tumors such as breast cancer, hepatocellular cancer, pancreatic cancer, and lung cancer." (PMID 33232284, 2020). "Consistent with the finding that FBP1 is often downregulated in human cancers, we provide compelling evidence that loss of FBP1 contributes to immune evasion of malignant tumors." (PMID 31938049, 2020). "Fructose-1, 6-biphosphatase (FBP1) is a key enzyme in gluconeogenesis and is implicated in human cancer due to its frequent loss in various cancer types." (PMID 31938049, 2020). "Loss of FBP1 expression in cancer cells has shown a critical role as oncogenic driver in EMT and BLBC." (PMID 29984231, 2018). "FUBP1 codes for the far upstream binding protein 1 (FUBP1 also named FBP1), which has an important role in cell proliferation and is implicated in multiple types of cancers." (PMID 24086756, 2013). "Moreover, FBP1 deficiency is associated with radiation and chemotherapy resistance and poor prognosis in cancer patients." (PMID 40100307, 2025). "Because FBP1 deletion contributes to PD-L1 upregulation and resistance to anti-PD-L1 therapy, FBP1 deletion may be associated with immune evasion in human cancers." (PMID 40100307, 2025). "In many cancers, loss of FBP1 is related to poor patient prognosis." (PMID 35404841, 2022). "FBP1 was originally identified as the rate-limiting enzyme in gluconeogenesis and loss of FBP1-mediated metabolic reprogramming that resulted in malignant behavior in cancer cells." (PMID 34363022, 2021). "In addition, loss of Fbp1 reportedly promotes apoptosis‐resistance in cancer stem‐like cells and enhances tumorigenesis." (PMID 33960626, 2021). "In addition, previous studies have shown that low levels of FBP1 are associated with low cancer survival rates and high relapse rates." (PMID 33232284, 2020). "Although FBP-1 is a Snail target gene, metabolic outcomes by loss of FBP1 in human cancer, whether increased mitochondrial flux or lactate production, are not yet well-understood, particularly under starved environment." (PMID 32927665, 2020). "Our findings also suggest that FBP1 loss may be a pervasive mechanism that contributes to the deregulation of PD-L1 in various human cancers." (PMID 31938049, 2020). "Evidence shows that the overexpression of FBP1 inhibits cell proliferation and significantly reduces tumor growth in various cancers." (PMID 40419474, 2025).
cancer (continued). "Although the roles of FBP1 in multifarious cancers have been described, but how nuclear FBP1 protein is regulated by posttranslational modifications remains poorly understood in ccRCC." (PMID 40419474, 2025). "In most cases, FBP1 is poorly expressed in cancers as an anti-oncogene, and its low expression predicts a bad prognosis for certain types of cancer." (PMID 40100307, 2025). "The silencing of fructose-1,6-bisphosphatase (FBP1) increases cancer cells’ reliance on glucose metabolism, concurrently reducing ROS levels through decreased mitochondrial respiration while enhancing NADPH production via the pentose phosphate pathway." (PMID 39857438, 2025). "Apart from its canonical role in glucose metabolism, FBP1 has been reported to be downregulated in certain cancers and correlated with patient survival." (PMID 40419474, 2025). "In cancer cells, FBP1 is usually inhibited, or its expression is reduced with implications on the EMT." (PMID 39997396, 2025). "The siRNA oligos for GLUL, ALDH2, BLVRA or FBP1 were introduced into cancer tissue derived CA-13 cells." (PMID 38580938, 2024). "ARHGAP26 and FAM53B were found associated with five cancer types, and PIP5K1C, FBP1, and CUL9 were found to be associated with four cancer types." (PMID 37187613, 2023). "Fructose‐1,6‐bisphosphatase (FBP1), a key rate‐limiting enzyme in gluconeogenesis, has been shown to play an important role in several diseases, including diabetes, asthma, and cancers." (PMID 36525508, 2023). "Collectively, these findings provided genetic evidence for FBP1 as a suppressor in a variety of cancers and suggested a genetic therapy for FBP1-induced improvement of gluconeogenesis." (PMID 35672803, 2022). "Our previous studies indicated that TRIM28‐dependent ubiquitination and USP44‐dependent deubiquitination of FBP1 regulated its stability in cancer cells." (PMID 34854226, 2022). "Overall, the inverse correlation between ALDOA and FBP1 was consistent in LUAD and LIHC cancer cell lines, supporting the clinical results that FBP1 and ALDOA have an interplay and correlation." (PMID 35404841, 2022). "FBP1 is a rate‐limiting enzyme in gluconeogenesis and mainly inhibits cancer cell progression in the cytoplasm." (PMID 34854226, 2022). "Beyond its catalytic activity, FBP1 inhibits aerobic glycolysis—known as the “Warburg effect”—in cancer cells." (PMID 36232688, 2022). "FBP is a particular metabolite in cancer, since both gluconeogeneic and glycolytic events require fructose-1,6-bisphosphatase 1 (FBP1) and ALDOA." (PMID 36077431, 2022). "Snail is an important mediator in cancer and has been shown to be increased in GC inducing the glucose metabolism via the down-regulated expression of FBP1 indirectly regulating the epithelial-mesenchymal transition (EMT)." (PMID 33407483, 2021). "In consistent with one recent study, we found that STAT3 is a potential target of FBP1 in cancer cells." (PMID 34363022, 2021). "We then found that enhanced FBP1 efficaciously reduced the malignancy of cancer cells, whereas FBP1 depletion did the opposite." (PMID 34363022, 2021). "The CNV or DNA methylation levels of some genes have been reported to regulate the expression of these genes in multiple cancer types, such as FBP1 in LIHC, GABPA in BLAC." (PMID 34222028, 2021). "Fructose‐1,6‐bisphosphatase (Fbp1) is one of the rate‐limiting enzymes in gluconeogenesis and plays a critical role in several cancers." (PMID 33960626, 2021). "In cancer research, FBP1 expression, a key gluconeogenetic enzyme, was inversely linked with Snail activation, a major activator of EMT, whereas FBP1 overexpression protected from EMT." (PMID 34778303, 2021). "As a gluconeogenesis regulatory enzyme, FBP1 had been further demonstrated play an important role in impairing aggressive phenotype in various cancers via a metabolic switch from glycolysis to oxidative phosphorylation (OXPHOS)." (PMID 32241279, 2020).
cancer (continued). "In summary, we discover a new role of FBP1 in antagonizing STAT3-dependent expression of PD-L1 and the mechanism through which FBP1 loss in human cancer cells contributes to the upregulation of PD-L1 and resistance to anti-PD-L1 treatment." (PMID 31938049, 2020). "In a physiologic condition, gluconeogenesis mainly occurs in liver and kidney under hypoglycemic condition, while FBP-1 is downregulated in specific types of human cancer." (PMID 32927665, 2020). "FBP1 was previously found to affect cell proliferation, migration and invasion in various cancer cells." (PMID 33232284, 2020). "The significance of these findings is further accentuated by our observations that expression of FBP1 and PD-L1 is negatively corrected in cell lines of multiple cancer types and PDAC patient specimens." (PMID 31938049, 2020). "FBP1 is regarded as a suppressor of tumors, and a decrease in FBP1 is positively correlated with the poor prognosis for people with carcinoma." (PMID 32439898, 2020). "Among these DANCR-regulated target genes, FBP1, a tumor suppressor gene identified in various cancers aroused our concern." (PMID 31383847, 2019). "MAGEA3-TRIM28 mediated proteasomal degradation of proteins like AMPKα1 or FBP1 are known mechanisms through which MAGEA3 provides a survival advantage to different cancer cells." (PMID 31287009, 2019). "This analysis revealed striking differences in how the metabolism of a leukemic cell differs from that of a T cell and identified specific potential targets for cancer therapy, including Hmgcs2, Prodh, Ldhb, Fbp1, and Chdh." (PMID 30140438, 2018). "We thus performed transwell assays to test the potential role of FBP1 expression on cancer cell invasiveness." (PMID 29984231, 2018). "In this study, we utilized the pyrosequencing analysis to further validate the mechanism of lower level mRNA of FBP1 in cancer tissues." (PMID 29984231, 2018). "There is evidence suggesting that fructose-1, 6-bisphosphatase 1 (FBP1) enzyme antagonizes glycolytic flux and is usually decreased in cancer cells." (PMID 28580187, 2017). "In summary, we identify TRIM28 as an E3 ubiquitin ligase of FBP1.MAGE-A3 and MAGE-C2 can bind with TRIM28 to form MAGE-TRIM28 cancer-associated ubiquitin ligase in HCC." (PMID 28394358, 2017). "An intriguing regulatory relationship between FBP1 and hypoxic responses was shown in ccRCC to oppose carcinoma progression." (PMID 29285300, 2017). "These included homozygous variants calls in genes related to cancer (BRCA1, APC, MEN1), congenital malformation syndromes (TCOF1), metabolic deficiencies (FBP1, HEXA), and neurological diseases (FUS, MLC1, DMD)." (PMID 26547235, 2015). "The Snail-G9a-DNMT1 protein complex has been shown not only to decrease E-cadherin levels but also FBP1, increasing glucose uptake, inducing glycolysis and cancer stem cell like characteristics." (PMID 25878567, 2015). "FBP1 is a transactivator of the c-myc gene, which is abundantly expressed in many cancers including HCC tumors." (PMID 25487856, 2014). "FBP1 is recognised as the key enzyme of gluconeogenesis, and upregulated FBP1 has been shown to suppress cancer cell growth; recent studies indicate that FBP2 participates in glycogen synthesis from carbohydrate precursors." (PMID 24063558, 2013). "We also showed that FBP1 functions as a TSG to suppress cancer cell growth through the induction of G2-M phase cell cycle arrest and an increase in ROS generation levels." (PMID 22039417, 2011). "However, numerous animal and clinical studies are needed to confirm the specific efficacy of HDAC inhibitors in cancers with low FBP1 expression." (PMID 40100307, 2025). "The observed upregulation of metabolic genes, such as ABCD2 and FBP1, following VD-LP treatment, suggests that the liposomal formulation may influence key pathways in cancer metabolism." (PMID 39931063, 2025).
cancer (continued). "However, the regulation of FBP1 remains poorly understood, despite several studies indicating that promoter methylation mediates FBP1 expression silencing in cancer." (PMID 40459008, 2025). "At the same time, high FBP1 level was related to a poor cancer prognosis." (PMID 39902328, 2025). "Restoration of FBP1 expression in cancer cells is expected to hold promise for cancer therapy." (PMID 40100307, 2025). "In addition to methylation and ubiquitination, which are essential for regulating FBP1 expression, other post-translational modifications play important roles in cancer biometabolism." (PMID 40100307, 2025). "FBP1 has been identified as an oncoprotein and is overexpressed in many types of malignant tumors." (PMID 40464853, 2025). "Conversely, the overexpression of FBP1 did not induce notable alterations in the expression of pathway markers within the Hedgehog pathway, which is also implicated in the regulation of cancer stem cell phenotype." (PMID 38349431, 2024). "We also analysed the expression of FBP1 in pan‐cancer and in the single‐cell transcriptome." (PMID 38693853, 2024). "However, FCN3, SLC22A1, ADH4, CYP2C8, SLC10A1, F9, and FBP1 were significantly downregulated in HCC tissue compared to the matched para-carcinoma tissue." (PMID 38664521, 2024). "Collectively, these findings indicated that overexpression of miR-24-1 activates FBP1 transcription by targeting active enhancers in the nucleus, and reactivated FBP1 then inhibits Warburg effect in cancer cells by slowing aerobic glycolysis, which finally blocks RCC progression." (PMID 35978816, 2022). "Importantly, while downregulation of FBP1 is associated with carcinogenesis in major human organs, restoration of FBP1 in cancer cells promotes apoptosis and prevents disease progression in solid tumors." (PMID 36232688, 2022). "Therefore, uncovering the effectors between ALDOA and FBP1 will lead to novel therapeutic strategies for cancer patients." (PMID 35404841, 2022). "FBP1 has been reported to be a critical oncogene in some cancers." (PMID 35672803, 2022). "FBP1 and ALDH2 are both involved in a signaling pathway linked to cancer metabolism." (PMID 36144737, 2022). "Targeting FBP1 has been an emerging therapeutical target for cancers." (PMID 36176391, 2022). "Moreover, restoration of FBP1 by overexpression of FBP1 in cancer cells was found to promote cell apoptosis and prevent disease progression in solid tumors." (PMID 36232688, 2022). "We next studied the distribution of FBP1 to determine whether it affects the sensitivity of cancer cells to PARP inhibitors." (PMID 34854226, 2022). "In recent years, the cancer-inhibiting role of FBP1 in has been mentioned in various studies." (PMID 36050791, 2022). "FBP1, a rate-limiting enzyme in gluconeogenesis, catalyzes the hydrolysis of fructose 1,6-bisphosphate to fructose 6-phosphate, playing a critical role in the energy metabolism of cancer cells." (PMID 35978816, 2022). "FBP1downregulation may be associated with DNA promoter hypermethylation and copy number loss, histone deacetylation (due to histone deacetylase deregulation), or post-transcriptional changes mediated by MAGE-TRIM28, leading to FBP1 degradation in cancer cells." (PMID 34830179, 2021). "The gluconeogenic enzyme FBP1 has been studied in the context of cancer." (PMID 34436420, 2021). "Forced Fbp1 expression also restores ROS generation in cancer stem‐like cells." (PMID 33960626, 2021). "Some studies have reported that Fbp1 can promote apoptosis in certain cancers." (PMID 33960626, 2021). "In addition, low expression of FBP1 was closely related to the drug resistance and the postoperative recurrence of the cancer." (PMID 33232284, 2020). "However, to the best of our knowledge, the phosphorylation of FBP1 has yet to be reported in cancer." (PMID 32754266, 2020).